NOD2 (nucleotide binding oligomerization domain containing 2)
Diseases named in the same sentence as NOD2 in open-access papers (continued):
Sharing a sentence is not in itself a finding about the gene and the disease.
uveitis (22 papers, 2008 to 2025). An inflammatory process affecting a part of or the entire uvea. "The first identified risk variant in CD patients, NOD2/CARD15, has also been associated with uveitis, suggesting a common pathogenic mechanism underlying uveitis and IBD development." (PMID 39956872, 2025). "Hotspot screening for NOD2 mutation can be incorporated as a screening tool while evaluating patients with uveitis for early diagnosis of this disease." (PMID 36189202, 2022). "Hotspot screening for NOD2 mutation can be incorporated as a screening tool while evaluating patients with uveitis for early diagnosis of BS." (PMID 36189202, 2022). "Our findings demonstrated that uveitis arises from inherent T cell dysfunction as a consequence of loss-of-function of Nod2." (PMID 33106495, 2020). "Collectively, these observations reveal a causal role for expansion of a pathogenic Th17-response in uveitis of Nod2−/− mice." (PMID 33106495, 2020). "Here the authors show, using Nod2-deficient mice and experimental uveitis, that Nod2 negatively regulates T cell activation and transcription of autoimmunity-related genes to suppress Th17 responses and uveitis." (PMID 33106495, 2020). "Our data thus far support a hematopoietic origin for the cellular mechanism by which Nod2 suppresses IRBP-induction of uveitis, which involves control over CD4+ T cells that cause organ-specific autoimmunity." (PMID 33106495, 2020). "In order to investigate the possible role of this gene in ACU, we have studied NOD2/CARD15 variants and the genotype-phenotype correlation in a cohort of patients with idiopathic uveitis and uveitis associated with other inflammatory diseases." (PMID 26438151, 2015). "NOD2 mutation is implicated in Blau, a rare autosomal dominant disorder characterized by early-onset granulomatous arthritis, uveitis and skin rash with camptodactyly." (PMID 22808176, 2012). "NOD2 promotes inflammation in Blau-syndrome-associated uveitis." (PMID 33670592, 2021). "In conclusion, that Nod2 functions as an endogenous protectant against uveitis has clear implications for development of therapeutic strategies to correct underlying T cell defects in uveitis and other forms of autoimmunity." (PMID 33106495, 2020). "The antimicrobial functions of Nod2 are well-established, yet the cellular mechanisms by which dysregulated Nod2 causes uveitis remain unknown." (PMID 33106495, 2020). "NOD2 polymorphisms are associated with ileal CD in Caucasians; in AA NOD2 may promote small bowel involvement, earlier onset, and fibro-stenotic disease uveitis and sacroiliitis." (PMID 20828408, 2010). "Based on criteria such as optic nerve head inflammation, retinal and choroidal infiltrates, hemorrhages, and retinal vasculitis, Nod2−/− mice developed significantly worse clinical uveitis." (PMID 33106495, 2020). "The in vivo contribution of Th17-immunity (over Th1-immunity) in Nod2-mediated uveitis was confirmed by neutralization studies." (PMID 33106495, 2020). "Lastly, an independent approach to test the T cell-autonomous function of Nod2 in uveitis was undertaken using naïve thymocytes in adoptive transfer studies with Rag1−/− hosts." (PMID 33106495, 2020). "Neutralization of IL-17 reduced uveitis severity in both WT and Nod2−/− mice, albeit to a greater extent proportionally in Nod2−/− mice." (PMID 33106495, 2020). "In family 3, the c.1412G>C p.(Arg471Pro) in NOD2 was found in the heterozygous state in all five family members, of which only one had a classical triad of BS including uveitis, and two had uveitis, one of whom had documented skin rush, while two exhibited camptodactyly only." (PMID 38927735, 2024). "Different mutations of nucleotide oligomerization domain containing the protein 2 gene (NOD2/CARD15) are associated with CD and may take part in the pathogenesis of uveitis in these patients." (PMID 38247834, 2024). "Here, we demonstrate a role for endogenous Nod2 within T cells in protection against uveitis." (PMID 33106495, 2020).
uveitis (continued). "Importantly, the exacerbated uveitis observed in Nod2−/− mice was CD4+ T cell-dependent, as depletion of CD4+ T cells ameliorated uveitis in both Nod2−/− mice and WT mice." (PMID 33106495, 2020). "The studies above excluded any host cellular function for Nod2 in suppression of uveitis." (PMID 33106495, 2020). "Since both Th1 and Th17 subsets can contribute to EAU28 we considered whether Nod2-mediated protection against uveitis involved regulation of a specific Th cell subset." (PMID 33106495, 2020). "The role of NOD2/CARD15 gene as a key regulator of innate immunity in the eye has been elucidated by studies performed on murine models,which are knockout for NOD2/CARD15, which showed an increased susceptibility to uveitis." (PMID 26438151, 2015). "Thus, we evaluated whether the T cell-intrinsic mechanism by which Nod2 suppresses uveitis involved the canonical Rip2-signaling axis." (PMID 33106495, 2020). "However we can't rule out a permissive effect of the NOD2 common variant in the development of uveitis." (PMID 26438151, 2015). "Here, we report a non-conventional, T cell-intrinsic function for Nod2 in suppression of Th17 immunity and experimental uveitis." (PMID 33106495, 2020). "Nod2-deficient CD4+ T cells produce more IL-17 and cause worse uveitis; a mechanism that is independent of Rip2-signaling or microbial stimuli, as MDP or in adjuvant." (PMID 33106495, 2020). "As with Nod2-mediated uveitis, the exacerbated pinealitis involved increased CD4+ T cells and CD4:CD8 ratio; thereby supporting an antigen-specific response by which Nod2 controls uveitis." (PMID 33106495, 2020). "Nod2−/− mice that were cohoused 1:1 with WT mice displayed exacerbated uveitis similar to that of non-cohoused Nod2−/− mice, suggesting that the Nod2-mediated phenotype is not influenced by the composition of transmittable microbiota." (PMID 33106495, 2020). "Reconstitution of lymphopenic hosts with Nod2−/− CD4+ T cells or retina-specific autoreactive CD4+ T cells lacking Nod2 reveals a T cell-autonomous, Rip2-independent mechanism for Nod2 in uveitis." (PMID 33106495, 2020). "Together, these data reveal a role for Nod2 in control over hyper-inflammatory Th17 cells and suppression of uveitis regardless of host-generated Nod2 or its cellular function in APCs." (PMID 33106495, 2020). "This supported a role for Nod2 that was not analogous to that of Rip2 in regulation of uveitis." (PMID 33106495, 2020). "Importantly, Nod2-mediated uveitis was IRBP-dependent, as WT and Nod2−/− mice treated with adjuvant alone showed no detectable pathophysiologic or clinical manifestations of disease." (PMID 33106495, 2020).
tuberculosis (19 papers, 2005 to 2025). A chronic, recurrent infection caused by the bacterium Mycobacterium tuberculosis. "Genetic studies also indicate the importance of NOD2 polymorphic alleles in association with the risk of tuberculosis caused by mycobacterium tuberculosis infection." (PMID 36146565, 2022). "In tuberculosis (TB), nonsynonymous variants of NOD2 were shown to be associated with active disease in a cohort of patients from Houston." (PMID 27297389, 2016). "A cohort study in 377 African Americans with tuberculosis found that certain SNPs in the NOD2 gene were associated with either resistance or susceptibility to tuberculosis." (PMID 24597572, 2014). "The gene mutations that encode mutant NOD2 proteins, however, appear to be rare in patients with tuberculosis." (PMID 17705850, 2007). "Interestingly, three common non-synonymous polymorphisms in the NOD2 gene were shown to be associated with genetic susceptibility to tuberculosis in African Americans." (PMID 36146565, 2022). "Moreover, in the Chinese Han population, another genetic polymorphism, Arg587Arg (CGT → CGG), located in exon 4 of the NOD2 gene, has been shown to be a possible risk factor for tuberculosis." (PMID 36146565, 2022). "NOD2 is also required for efficient antibacterial innate and adaptive immunity in the chronic phase of pulmonary M. tuberculosis infection, and polymorphisms in the human NOD2 gene have been associated with resistance or susceptibility to tuberculosis." (PMID 24312100, 2013). "The present study aimed to investigate the genetic polymorphisms in exon 4 of the NOD2 gene in tuberculosis patients and healthy controls, in order to clarify whether polymorphisms in the NOD2 gene is associated with tuberculosis." (PMID 22502597, 2012). "The odd ratio of 2.16 (95% CI = 1.31-3.58; P < 0.01) indicated that the Arg587Arg SNP in NOD2 may be associated with susceptibility to tuberculosis in the Chinese Han population." (PMID 22502597, 2012). "Interestingly, preliminary data indicate that mycobacterial antigens regulate the expression of NOD2 splice variants and further studies are required to clarify their role in tuberculosis." (PMID 17705850, 2007). "The polymorphism of the NOD2 gene is related to the risk of tuberculosis (TB), an infectious disease caused by Mycobacterium tuberculosis (Mtb), which poses serious ongoing challenges to global public health." (PMID 41017210, 2025). "For example, Bacille Calmette Guérin (BCG) vaccine utilized an attenuated strain of Mycobacterium bovis protect chronic infection disease threats such as tuberculosis (TB) through activating NOD2." (PMID 33553427, 2021). "We further demonstrate that Inarigivir boosts the efficacy of the BCG vaccine against tuberculosis in mice and represents a new generation of adjuvants that target NOD2/RIG-I signaling and perhaps they can be safely combined with other vaccines." (PMID 33365029, 2020). "NOD2 does not play a significant role in controlling M. tuberculosis growth during early infection, although NOD2 mRNA levels are increased in patients with tuberculosis." (PMID 22851964, 2012). "Nonetheless, the increased levels of NOD2 expression in some patients with severe tuberculosis, and the increases in expression levels within peripheral leucocytes following treatment merit further studies in selected patient and control populations." (PMID 17705850, 2007). "In whole blood, NOD2 mRNA levels increased significantly after completion of anti-tuberculosis treatment." (PMID 17705850, 2007). "We were surprised to find significantly higher levels of NOD2 mRNA expression in peripheral leucocytes obtained from patients who completed anti-tuberculosis therapy." (PMID 17705850, 2007). "In pulmonary leucocytes obtained from patients with tuberculosis, NOD2 mRNA expression correlated with TLR2 (p = 0.02) and TLR4 (p = 0.01) but not with TLR6 mRNA expression (p = 0.17)." (PMID 17705850, 2007).
tuberculosis (continued). "Regarding the role of NOD2 in tuberculosis, one must, however, acknowledge that the present study provides information only on the in vitro recognition of M. tuberculosis, and studies investigating the role of NOD2 in infection models are warranted." (PMID 16322770, 2005). "Nevertheless NOD2 mutations have not been firmly established as a risk factor for tuberculosis and several studies argue against such a correlation." (PMID 24597572, 2014). "Our study is the first to demonstrate that the Arg587Arg SNP in NOD2 is a new possible risk factor for tuberculosis in the Chinese Han population, but not in the Uyghur and Kazak populations." (PMID 22502597, 2012). "In conclusion, using in vitro and in vivo experimental models of tuberculosis, we demonstrate that a combined activation of cytosolic receptors RIG-I and NOD2 can amplify a protective immune response induced by the BCG vaccine against TB." (PMID 33365029, 2020). "Thus, NOD2 mutations may be the common risk factor for both patients to develop intestinal failure requiring HPN and to acquire or reactivate tuberculosis, in these two cases tuberculous lymphadenitis." (PMID 24597572, 2014). "One could argue that the receptors and pathways involved in candida (C-type lectin receptors) and tuberculosis (TLR 2 and NOD2) are less affected by opioids." (PMID 25830312, 2015). "Nod2 triggers cytokine production by DCs in response to live M. tuberculosis, but is not essential to control M. tuberculosis airway infection." (PMID 19360122, 2009). "Our gene expression studies revealed that there are no characteristic NOD2 transcriptional responses in pulmonary leucocytes obtained from patients with tuberculosis." (PMID 17705850, 2007).
Yao syndrome (19 papers, 2021 to 2026). An an autoinflammatory disease characterized by periodic fever, dermatitis, arthritis, and swelling of the distal extremities, as well as gastrointestinal and sicca-like symptoms. "Yao syndrome is associated with specific mutations in the NOD2 gene located on chromosome 16, including notably NOD2 IVS8+158 and R702W." (PMID 39006711, 2024). "The majority of patients with Yao syndrome exhibit the NOD2 IVS8+158 mutation, and approximately 30% also carry the concurrent R702W variation." (PMID 39006711, 2024). "Yao syndrome (YAOS) is formerly called nucleotide-binding oligomerization domain containing 2 (NOD2)-associated autoinflammatory disease.We report a large cohort of YAOS." (PMID 39372397, 2024). "Characteristics of 11 patients with NOD2 variants and diagnoses other than Yao syndrome in the present study." (PMID 38348033, 2024). "Another NOD2-associated disease is Yao syndrome (YAOS, OMIM #617321), formerly designated NOD2-associated autoinflammatory disease." (PMID 37928541, 2023). "Central to the genetic underpinnings of Yao syndrome are mutations in the NOD2 gene." (PMID 39006711, 2024). "Yao syndrome, a rare autoinflammatory disorder linked to mutations in the nucleotide-binding oligomerization domain-containing protein-2 (NOD2) gene, manifests through periodic fever, polyarthritis, dermatitis, gastrointestinal disturbances, and sicca-like symptoms." (PMID 39006711, 2024). "Yao syndrome, formerly broadly referenced as NOD2-associated autoinflammatory disease, is a genetically complex multifactorial disease characterized by periodic fever, dermatitis and inflammatory arthritis and gastrointestinal symptoms without inflammatory bowel disease." (PMID 37869013, 2023). "Differential diagnosis should be extended to include another NOD2-associated disease, Yao syndrome." (PMID 36465324, 2022). "The presence of a particular NOD2 genetic variant (c.2798 + 158C > Talone or associated with c.2023C > T-p.Arg675Trp) has been linked to the development of Yao Syndrome or NOD2- associated AID (NAID), a multisystemic inflammatory disease presenting in adulthood." (PMID 34198614, 2021). "The study investigated the pathogenesis of Yao syndrome (YAOS), a rare systemic autoinflammatory disease associated with the nucleotide-binding oligomerization domain containing 2 (NOD2) gene variants." (PMID 38395960, 2024). "Yao syndrome (YAOS, OMIM# 617321), originally named nucleotide-binding oligomerization domain containing 2 (NOD2)-associated autoinflammatory disease (NAID), is a systemic autoinflammatory disease (SAID) first reported by Yao and colleagues in 2011." (PMID 38395960, 2024). "Recently, specific NOD2 variants (IVS8 + 158 and R702W), have been linked to Yao syndrome." (PMID 37869013, 2023). "Yao syndrome (YAOS, OMIM# 617321) is a kind of systemic autoinflammatory diseases (SAIDs) linked to the nucleotide-binding oligomerization domain containing 2 (NOD2)." (PMID 39290705, 2024). "NOD2 genetic variations are associated with diseases such as Crohn’s disease (CD, OMIM 266600), Blau syndrome (BS, OMIM 186580), and Yao syndrome (YAOS, OMIM 617321)." (PMID 39372397, 2024).
asthma (17 papers, 2007 to 2025). "provided more data supporting the implication of NOD2 polymorphisms in respiratory atopy in an adult cohort, and importantly, showed a significant association of rs1077861 and rs3135500 with asthma development." (PMID 36189256, 2022). "Nucleotide-binding oligomerization domain 2 (NOD2) recognizes pathogens associated with the development of asthma." (PMID 36233196, 2022). "In summary, this study provided evidence that the NOD2 gene rs3135499 polymorphism genotypes differed between children with asthma and healthy children in the Chinese Han population." (PMID 30950247, 2019). "The purpose of this study was to explore the relationship between NOD2 gene polymorphisms and asthma susceptibility in the Chinese Han population." (PMID 30950247, 2019). "In this study, we have analyzed the potential associations of polymorphisms in the NOD2 gene with asthma in Chinese population." (PMID 30950247, 2019). "Previous studies have found that NOD2 polymorphism is associated with asthma in the German population." (PMID 30950247, 2019). "The rs3135499 polymorphisms in the NOD2 gene was significantly associated with asthma in the Chinese Han population." (PMID 30950247, 2019). "It is of interest that NOD2 recognizes Streptococcus pneumoniae as well as viruses such as the respiratory syncytial virus, which are two childhood infections increasing the risk of developing asthma in adulthood." (PMID 36233196, 2022). "Similarly, different authors have reported results supporting the existence of a genetic link between the polymorphisms in the NOD2 gene and asthma development." (PMID 36189256, 2022). "It was reported that the NOD2 gene is significantly overexpressed in human airway smooth muscle cells (HASMC) in asthma patients and could be considered a potential diagnostic biomarker and a therapeutic option in this disease." (PMID 34440800, 2021). "NOD2 polymorphisms have been associated with increased risk of developing asthma." (PMID 34440800, 2021). "Therefore, the aim of this research was to identify the role of NOD2 polymorphisms in the genetic basis of asthma in the Chinese population and to evaluate the relationship between the NOD2 polymorphisms and the serum level of interferon‐β." (PMID 30950247, 2019). "Different experimental models have been used to explore and confirm the findings obtained in human samples and in vitro studies regarding the implication of NOD1 and NOD2 in different aspects related to asthma pathophysiology." (PMID 36189256, 2022). "Since NOD2 expression is increased in human bronchial SMC from asthma patients and MDP promotes their proliferation and migration, the effect of MDP co-administration on airway remodeling was examined in the dog-allergen model." (PMID 36233196, 2022). "Despite this fact, the reported results seem to indicate that there are differences in the implication of NOD1 and NOD2 in the lung epithelium in the context of asthma." (PMID 36189256, 2022). "Nonetheless, due to the limited sample size and the specific genetic characteristics of the Chinese population, the pathogenesis of NOD2 in asthma needs further study to verify our results." (PMID 30950247, 2019). "The nucleotide‐binding oligomerization domain 2 (NOD2) has been involved in the pathogenesis of asthma." (PMID 30950247, 2019). "NOD2 can influence macrophages, other innate cells, and cytokines relevant to allergenic asthma." (PMID 39507249, 2024). "Hitherto, few studies have been published on the effect of NOD2 in asthma models." (PMID 36233196, 2022). "We, therefore, used our recently developed Th2/Th17 mixed asthma model to evaluate if the NOD2 pathway may favor development of this disease." (PMID 36233196, 2022).